RET (ret proto-oncogene)
Diseases named in the same sentence as RET in open-access papers (continued):
Sharing a sentence is not in itself a finding about the gene and the disease.
breast carcinoma (continued). "In breast cancer, increased levels of the receptor tyrosine kinase REarranged during Transfection (RET) proto-oncogene have been observed in tumors compared to surrounding healthy tissue, and high RET expression has been associated with tamoxifen and AI resistance in ER+ breast cancers." (PMID 39931212, 2024). "The presence of RET missense mutations in ER+ breast cancers, a subset which may be hormone therapy resistant, becomes highly relevant and merits further study given known associations between RET expression levels and reduced sensitivity to hormonal therapies." (PMID 30446652, 2018). "The RET signaling network has been shown to affect multiple axes of breast cancer, including tumor development, metastasis, and treatment resistance." (PMID 40842594, 2025). "Since the late 1980s, the proto-oncogenic role of RET has been identified and characterized in numerous cancer types, including thyroid, lung, and breast cancer, with RET alterations occurring in less than 5% of all cancer patients." (PMID 40243903, 2025). "The aberrant activation of RTKs, particularly by RET fusion and mutation, is implicated in numerous cancers, spanning non-small-cell lung cancer (NSCLC) to breast cancer." (PMID 39086985, 2024). "Despite these encouraging results, further investigation is needed to fully understand the potential role RET inhibition in breast cancer." (PMID 39211557, 2024). "The functional role of RET was assessed by siRNA-mediated RET silencing and targeted inhibition with the FDA/EMA-approved RET-selective inhibitor selpercatinib in resistant breast cancer cells and patient-derived organoids (PDOs)." (PMID 39931212, 2024). "Although there are clinical reports indicating the efficacy of selpercatinib in the treatment of RET fusion-positive breast cancer, the number of articles is limited, and the effects of this RET inhibitor on patient estrogen levels remain under-investigated." (PMID 39777333, 2024). "These molecules showed notable efficacy in the treatment of RET-driven tumors, including some breast cancer cases." (PMID 39211557, 2024). "We further found that RET silencing using RET-specific siRNAs significantly inhibited the growth of MCF7-derived ER+ breast cancer cells resistant to combined CDK4/6i and endocrine therapy (MPF-R) but not of T47D-derived double-resistant cell line (TPF-R)." (PMID 39931212, 2024). "We show that RET is upregulated in ER+ breast cancer cell lines resistant to combined CDK4/6i and fulvestrant compared to isogenic cells resistant to fulvestrant alone." (PMID 39931212, 2024). "The link between RET and ER+ breast cancer suggests RET expression can modulate breast cancer cell motility and metastasis." (PMID 39000231, 2024). "Limited preclinical evidence has been generated in BC models harboring RET rearrangements with the available evidence indicating that cabozantinib reduces the proliferative potential of breast cancer cells displaying the NCOA4-RET fusion." (PMID 39211557, 2024). "Currently, both mTOR inhibitors and inhibitors to upstream mTOR mediators, such as RET, are candidate therapies for metastatic HR+ breast cancer." (PMID 39000231, 2024). "This study shows that RET overexpression is associated with resistance to combined CDK4/6i and fulvestrant treatment in ER+ breast cancer cell lines." (PMID 39931212, 2024). "RET then activates signaling cascades to phosphorylate ERα, forming an SE-controlled positive feedback loop that facilitates breast cancer proliferation." (PMID 38844984, 2024). "Previous studies have shown that RET induces estrogen-independent ERα phosphorylation and expression of ER target genes in ER+ breast cancer cells." (PMID 39931212, 2024). "Prior RNA sequencing studies of primary and matched brain metastasis have identified RET as a highly upregulated kinase in breast cancer." (PMID 39000231, 2024).
breast carcinoma (continued). "In breast cancer, and especially in the estrogen receptor-positive (ER+) subtype, the activity of RET is of notable importance." (PMID 39211557, 2024). "In this review, the physiological function of RET in normal development is outlined and compared with current clinical and scientific appraisal of RET’s oncogenic contributions across multiple cancers and with a focus on breast cancer." (PMID 36918928, 2023). "An additional screening study of 4871 patient samples from cancers of diverse origin identified RET alterations in 3 of 506 breast cancer samples (a frequency of 0.6%)." (PMID 36918928, 2023). "Here, we review breast cancer-specific studies of RET alterations and where relevant, their relationships with specific breast cancer molecular subtypes and disease stages." (PMID 36918928, 2023). "RET expression is significantly correlated with ER-positivity in large-scale analyses of patient tissue, suggesting a specialized role for RET in ER+ breast cancer." (PMID 36918928, 2023). "In breast cancer, RET signaling networks have been shown to influence diverse functions including tumor development, metastasis, and therapeutic resistance." (PMID 36918928, 2023). "Preclinical models demonstrated the transforming capacity of both RET fusions and amplifications in breast cancer cell lines through activation of the MAPK and PI3K pathways." (PMID 37627175, 2023). "This review discusses in depth the interactions between RET and the key breast cancer drivers ERα and HER2, in addition to regulators of inflammatory response, cellular motility, and tumor growth." (PMID 36918928, 2023). "Given the evidence suggesting a role for RET in breast cancer brain metastasis, the intracranial activity of modern RET inhibitors highlights importance of blood–brain barrier permeability, a design feature of multiple modern kinase inhibitors." (PMID 36918928, 2023). "RET amplifications have been observed in several other tumor types, including hepatobiliary cancers, prostate cancer, breast cancer, glioblastoma, stomach adenocarcinoma, colorectal adenocarcinoma, and bladder urothelial carcinoma." (PMID 37627175, 2023). "While further study of the specific clinical role of RET fusions is required, the response of the patient described highlights an urgent need for the examination of RET alterations during planning of breast cancer therapeutics." (PMID 36918928, 2023). "While RET expression in the normal human breast is negligible in both development and adulthood, RET has been shown to mediate multiple aspects of breast cancer development and progression, which are reviewed below." (PMID 36918928, 2023). "High-RET expression has been shown to correlate with shorter metastasis-free and overall survival in breast cancer." (PMID 39516358, 2023). "Breast cancer (BC) is the most common cancer in women, with approximately 1.7 million people diagnosed every year, and RET alteration occurrence is approximately 1.2%." (PMID 36865807, 2023). "ER is a central transcription factor in breast cancer, inducing both RET and GFRA1 gene expression, which reciprocally function to enhance estrogen-driven cell proliferation." (PMID 36918928, 2023). "The essential role of the GFRα family proteins in RET-mediated signal transduction has been recapitulated in breast cancer cell lines, with GFRα1 expression a limiting factor for GDNF-mediated signal activation in multiple in vitro studies." (PMID 36918928, 2023). "RET’s propensity to drive breast cancer metastasis, along with an emerging role for RET in brain-tropic metastatic colonization, highlight two critically important functions warranting further investigation." (PMID 36918928, 2023). "While these pathways can be activated by a number of receptor tyrosine kinases, it is clear that RET can act as a key player in the mediation of these intracellular signaling pathways in breast-cancer specific settings." (PMID 36918928, 2023).
breast carcinoma (continued). "The molecular role of RET as an oncogenic driver is then examined, including a summary discussion of RET alterations across cancers, with an emphasis on breast cancer-specific reports." (PMID 36918928, 2023). "In breast cancer, RET has been primarily studied in the context of estrogen-receptor positive (ER+) disease." (PMID 36918928, 2023). "Prospective trials have since provided evidence of confirmed responses and sustained disease control in a proportion of RET-altered thyroid, lung, and breast cancer patients treated with RET MKIs." (PMID 37627175, 2023). "Gains in RET expression have been reported in multiple in vitro models of endocrine therapy-resistant breast cancer, including long-term estrogen deprived, tamoxifen-resistant, and aromatase-overexpressing breast cancer cell lines." (PMID 36918928, 2023). "RET genomic alterations, however, are relatively rare in breast cancer, reported in approximately 1.2% of cases." (PMID 36918928, 2023). "Further, publicly available RNASeq data demonstrates the presence of RET expression in multiple HER2+ breast cancer cell lines, highlighting a potential area for future study." (PMID 36918928, 2023). "In this review, we provide examples of the role for RET signaling in multiple facets of breast cancer progression, along with the known functions for RET overexpression and alterations across breast cancer subtypes." (PMID 36918928, 2023). "This review assesses the status of research on RET in breast cancer and evaluates the therapeutic potential of RET-selective kinase inhibitors across major breast cancer subtypes." (PMID 36918928, 2023). "The proto-oncogenic role of RET has been identified and characterized in numerous cancer types, such as, thyroid, lung, and breast cancers." (PMID 35957881, 2022). "A study by Gattelli and colleagues determined that RET activation promotes growth, proliferation, and migration of ER+ breast cancer cells in vitro and in vivo, strongly suggesting that RET is actionable in ER+ breast cancers." (PMID 35957881, 2022). "In 2013, the Isacke group determined that RET signaling is hyperactivated in aromatase-resistant ER+ breast cancer and that pharmacological RET inhibition impairs GDNF-mediated aromatase inhibitor resistance." (PMID 35957881, 2022). "In other words, GDNF-mediated GFR/RET activation promotes breast cancer proliferation and migration." (PMID 35582425, 2022). "We identified RET gene overexpression as a breast cancer driver; however, its function in the mammary gland remains understudied." (PMID 35044452, 2022). "RET is altered in ~1.2% of breast cancer cases, of which 66% are RET amplifications and 7% are activating fusions." (PMID 35957881, 2022). "determined that RET regulates sensitivity of ER+ breast cancer cells to endocrine therapies and that activated RET promotes estrogen-independent activation of ERα, suggesting that RET and ERα pathway crosstalk in endocrine-resistant breast cancers." (PMID 35957881, 2022). "Albeit rare, an ERBB2 fusion identified in a patient with HER2+ breast cancer and an acquired RET fusion identified in a patient with an acquired ESR1, offer interesting insights into subtype-specific resistance mechanisms and warrant further investigation." (PMID 36470901, 2022). "In other tumor types such as breast cancer and salivary gland carcinomas, RET alterations can be found at lower frequencies." (PMID 35957881, 2022). "Although RET is extensively involved in the development of breast cancer, GFRα is indispensable and irreplaceable in driving endocrine resistance, thus contributing to cell survival." (PMID 35582425, 2022). "Early investigations of RET in breast cancer were primarily focused on estrogen receptor-alpha-positive (ER+) cases due to the prevalent co-overexpression of RET and its co-receptor, GFRα1, in a subset of ER+ breast cancers." (PMID 35957881, 2022).
breast carcinoma (continued). "In summary, these findings suggest that RET is actionable in breast cancers, especially those of HER2-enriched and triple-negative subtype." (PMID 35957881, 2022). "Sunitinib, an inhibitor of RET, is often used to target the receptor tyrosine kinase in Tam resistance ER+ breast cancers." (PMID 36419768, 2022). "While RET fusions are detected in other cancers, such as breast cancer and salivary gland carcinomas (discussed later), RET fusions occur in these cancer types at much lower frequencies (0.16% and 3.2%, respectively)." (PMID 35957881, 2022). "Despite our findings and other research insights in mammary cancer models, the connection between RET and inflammation remains understudied." (PMID 35044452, 2022). "Using the Ret/MTB mouse model, we have previously shown that chronic overexpression of WT RET gene in the mammary epithelium induces hyperplasia and mammary tumors." (PMID 35044452, 2022). "TFAP2C interactions with PELP1 confer a growth advantage to breast cancer (BC) cells by activating an oncogenic RET signaling thus contributing to BC progression and therapy resistance." (PMID 33269540, 2021). "Paratala and colleagues profiled RET fusions in breast cancer and identified CCDC6-RET, NCOA4-RET and RASGEF1A-RET." (PMID 34650924, 2021). "LIBRETTO-001 continues to enroll patients with RET fusion–positive solid tumors, including breast cancer." (PMID 34036231, 2021). "ST3GAL1 silencing increased sensitivity to a combination of RET inhibitor vandetanib and ER inhibitor tamoxifen in ERα-positive breast cancer cells." (PMID 33921986, 2021). "Continued characterization of the overall frequency of RET fusions in breast cancer and other solid tumors is warranted." (PMID 34036231, 2021). "DOK4 is a positive regulator of the mitogen-activated protein kinase (MAPK) pathway, and it undergoes phosphorylation by the RET tyrosine kinase, whose over-expression is observed in estrogen receptor (ER)-positive breast cancer." (PMID 32370309, 2020). "Studies have correlated RET gene expression with shorter metastasis-free survival and OS in breast cancer." (PMID 32370309, 2020). "The pharmacological inhibition of RET with panspecific kinase inhibitors restores the sensitivity of breast cancer cell lines to tamoxifen, fulvestrant, and letrozole." (PMID 32993133, 2020). "Using hybrid capture targeted genomic profiling of RET introns 9-11 and all exons, a study in 9693 cases of breast cancer identified 121 RET alterations." (PMID 35582449, 2020). "Large-scale analyses have reported that RET fusion can be detected in 0.2% of colorectal cancers (6/3117 cases) and 0.1% of breast cancers (8/9693 cases)." (PMID 33150251, 2020). "RET is a transcriptional target of estrogen receptor alpha (ESR1) and several studies have reported its overexpression, particularly in ER+ breast cancer as well as its association with endocrine resistance." (PMID 32326537, 2020). "In a recent study based on targeted genomic profiling of 9693 cases, RET genomic alterations, including 16 rearrangements, were observed in 1.2% of breast cancers." (PMID 32326537, 2020). "In cancer promotion function, GFRA1 gene can encode GFRA1 protein to promote tumor progression by activating RET and downstream pathways in breast cancer and pancreatic cancer." (PMID 33175846, 2020). "RET and its coreceptors therefore represent viable therapeutic targets for use in conjunction with current breast cancer therapies, and GFRα1 has recently been assessed as a target for antibody-drug conjugates." (PMID 33233403, 2020). "Though initially believed to be PTC-specific, RET gene fusions have more recently been identified in several cancer types, including lung, colon, and breast carcinoma." (PMID 32326537, 2020). "Recent studies have also identified RET fusions in lung and colon adenocarcinoma, breast cancer as well in MTCs, a more aggressive form of thyroid cancer." (PMID 32345963, 2020).
breast carcinoma (continued). "In the present study, we analysed the role of RET expression in a large cohort of 990 primary breast cancer cases and correlated the expression with clinicopathological parameters and survival data." (PMID 30621641, 2019). "Due to the important role of IL-6 in breast cancer cell migration, RET not only seems to have an impact on tumour growth but also on metastasis." (PMID 30621641, 2019). "Since its initial discovery RET has increasingly gained importance in multiple cancer types including breast cancer." (PMID 30621641, 2019). "In summary, due to its specific role in endocrine resistance as well as the possible correlation with poor prognosis, RET remains a promising therapeutic target in breast cancer." (PMID 30621641, 2019). "While specific RET inhibitors are only beginning to emerge, two different types of inhibitory agents are currently evaluated within preclinical and clinical trials in breast cancer." (PMID 30621641, 2019). "We performed an immunohistochemical analysis of RET protein expression on a tissue microarray encompassing 990 breast cancer patients and correlated its expression with clinicopathological parameters and survival data." (PMID 30621641, 2019). "The Rearranged during Transfection (RET) protein is overexpressed in a subset of Estrogen Receptor (ER) positive breast cancer, with both signalling pathways functionally interacting." (PMID 30621641, 2019). "To further investigate the role of RET expression in human breast cancer we performed an immunohistochemical analysis on breast cancer tissue microarrays (TMA) with detailed clinical and survival data." (PMID 30621641, 2019). "This cross-talk plays a pivotal role in the resistance of breast cancer cells to anti-endocrine therapies, and RET expression is assumed to correlate with poor prognosis based on findings in small patient cohorts." (PMID 30621641, 2019). "The aim of our study was to investigate the impact of RET expression on patient outcome in human breast cancer." (PMID 30621641, 2019). "Of all variant classes, RET amplifications were the most commonly observed and mainly found in ER− and ERBB2− (ERBB2 wild-type/HER2-) breast cancers, followed by missense mutations and rearrangements." (PMID 30446652, 2018). "The response of the RETamp xenografts to cabozantinib also reveals the potential for RET inhibition in treating RET amplification-positive breast cancers although this needs to be corroborated with appropriate patient-derived xenograft models." (PMID 30446652, 2018). "Using targeted genomic profiling with hybrid capture that includes analysis of introns 9, 10, and 11 of RET, high-level analysis of genomic alterations of RET in a variety of breast cancer subtypes are presented here." (PMID 30446652, 2018). "In in vitro cell and animal models of breast cancer, activation of RET signaling by GFLs enhances tumor cell proliferation, and survival and has been shown to promote estrogen-independent expression of a normally estrogen-ER-dependent transcriptional profile." (PMID 30666215, 2018). "The minimally amplified region around RET in this breast cancer cohort cannot be determined from targeted genomic profiling alone." (PMID 30446652, 2018). "Novel rearrangements and previously reported fusions in RET were identified in this comprehensive cohort of advanced breast cancer patients." (PMID 30446652, 2018). "Antibody-drug conjugates targeted to RET or GFRα1, have demonstrated effective and specific killing of breast cancer cells in vitro and in vivo." (PMID 30666215, 2018). "The RET tyrosine kinase signaling pathway is involved in the development of endocrine resistant ER+ breast cancer." (PMID 29608602, 2018). "The novel RASGEF1A-RET fusion was detected in an ER−/PR−/HER2− breast cancer and results from an inversion event on chromosome 10 with breakpoints in RASGEF1A intron 1 and RET intron 9 that juxtaposes the 5′UTR of RASGEF1A upstream of the RET kinase domain." (PMID 30446652, 2018).